SPHK1 (sphingosine kinase 1)
Diseases named in the same sentence as SPHK1 in open-access papers (continued):
Sharing a sentence is not in itself a finding about the gene and the disease.
tumor (continued). "The short-term efficacy of androgen depletion was confirmed in vivo using an orthotopic model of xenotransplanted LNCaP cells where castration could not only noticeably reduce tumor size and metastasis dissemination but also induce a significant SphK1 inhibition." (PMID 19956567, 2009). "SphK1 is highly expressed in HCC tissues, while SphK2, although less studied in HCC, can influence tumor cell behavior through regulation of gene expression and cell cycle progression." (PMID 41234914, 2025). "IHC staining of post-treatment intracranial tumor sections quantified the expression of M2 macrophage markers ENO1, CD163, and phosphorylated SPHK1 (p-SPHK1)." (PMID 41353343, 2025). "In terms of therapeutic target research, SphK1 inhibitors (such as PF-543 and SKI-178) significantly suppress tumor progression by selectively inhibiting activity or jointly targeting S1P lyase." (PMID 41234914, 2025). "Clinical evidence shows that SphK1 mRNA expression is significantly upregulated in tumor tissues of HCC patients, and its expression level is positively correlated with tumor progression and poor prognosis." (PMID 41234914, 2025). "In targeted therapy, SphK1 inhibitors (e.g., PF-543) and SphK2 inhibitors (e.g., ABC294640) have shown significant anti-tumor effects in preclinical models." (PMID 41234914, 2025). "Inhibition of SphK1 with PF‐543 has been shown to disrupt PFKFB3‐mediated glycolysis, thereby impairing tumor angiogenesis." (PMID 41427031, 2025). "Sphingosine kinase 1 (SK1) inhibitors reduce immunosuppressive cytokines such as TGF-β and IL-10, while enhancing CD8+ T cell function and the tumor’s response to ICI." (PMID 40872475, 2025). "In conclusion, SPHK1/S1P axis is hyperactivated in CRC patients with poor prognosis and promotes angiogenesis by increasing VEGFA expression in both tumor cells and M2 macrophages." (PMID 40589755, 2025). "SPHK1 inhibition by PF‐543 or shRNA knockdown in SKOV3 cells also significantly reduced tumour formation and tumour metastases in a mouse xenograft." (PMID 40356021, 2025). "Conversely, knocking down SPHK1/MMP1 downregulated PD-L1+ cells and relatively increased the density of CD8+ T cells in the tumor area." (PMID 39629135, 2024). "Given the critical role of tumor neovascularization in HCC progression and the pro-angiogenic effects of SphK1, we examined the impacts of PF-543 on intratumoral vessel density in DEN-induced HCC." (PMID 38200582, 2024). "In the animal study, it is further demonstrated that inhibition of SPHK1 by PF-543 (a SPHK1 inhibitor) and/or inhibition of ATF4 by vemurafenib (a BRAF inhibitor to reduce ATF4 production) can inhibit the growth of TMZ-resistant GBM tumor." (PMID 39090107, 2024). "Transcription factor E2F1 regulates sphingosine kinase 1 (SPHK1), which is known to promote angiogenesis, and a contribution of HULC/E2F1/SPHK1 axis in augmenting tumor angiogenesis was shown." (PMID 38203767, 2024). "However, the specific mechanisms of SPHK1 involvement in tumor immune evasion remain unclear." (PMID 39629135, 2024). "After euthanizing the mice and harvesting the tumors, immunofluorescence staining revealed that SPHK1/MMP1 overexpression significantly enhanced PD-L1+ cell counts and decreased the density of CD8+ T cells within the tumor region." (PMID 39629135, 2024). "Building upon the identification of the active form of SphK1 as a viable therapeutic target in human HCC specimens, we assessed the capacity of PF-543 in suppressing tumor progression using a diethylnitrosamine-induced mouse model of primary HCC." (PMID 38200582, 2024). "To investigate the effects of SPHK1 and MMP1 expression on tumor biology, we initially generated SCC7 cells from HNSCC mice with normal immune function and stably overexpressed or knocked down SPHK1 or MMP1." (PMID 39629135, 2024).
tumor (continued). "Among tumor-related genes characterizing Clusters I and II, differences in the levels of DNA methylation and mRNA expression for the SPHK1, INHBA, LTB and PDE3B genes were correlated with poorer tumor differentiation." (PMID 36348017, 2023). "In our present set of tissue samples, differences in DNA methylation levels resulting in differences in the mRNA expression levels of the SPHK1, INHBA, LTB and PDE3B genes were correlated with poorer tumor differentiation." (PMID 36348017, 2023). "Further blocking SPHK1 with its inhibitor, PF543, also improved the cytotoxicity of those T cells in tumor ascites." (PMID 35289120, 2022). "More than half (52.2%) showed high positivity in tumor cells, whereas low IRS for SphK1 was observed in 47.8% of patients." (PMID 35494957, 2022). "Based on the central role of SphK1 in NEPC development, small molecule‐specific inhibitors can overcome Enzalutamide resistance as well as tumor growth of several clinically relevant NEPC models and decrease NE biomarkers in PDE." (PMID 35184376, 2022). "SphK1 protein levels were decreased, while the total ceramide levels were increased in GNE-493-treated tumor tissues." (PMID 35296639, 2022). "We have determined the protein expression of four S1P-metabolizing enzymes (SphK1, SphK2, sphingosine-1-phosphate phosphatase 1 (SGPP1), and lipid phosphate phosphatase 3 (LPP3)) by immunohistochemistry (IHC) in tumor tissues of 46 OSCC patients." (PMID 35494957, 2022). "Evidence from past literature demonstrates that SPHK1 enhances the production of MMP-2 and MMP-9 and thereby promotes tumor proliferation and invasion of colon cancer." (PMID 36309544, 2022). "However, the detailed mechanisms of the involvement of SPHK1 in tumor immune escape remain unknown." (PMID 36050478, 2022). "In the present study, protein expression of both SPHK1 (*p = 0.041) and CERK (**p = 0.0028) were found to be significantly upregulated in tumor tissue as compared to adjacent normal tissue." (PMID 36309544, 2022). "Ten days after the tumor cells were injected, the mice were randomized and treated with EVs isolated from i) parental ID8 cells, ii) ID8 cells that EE SPHK1, or (iii) SPHK1−/− ID8 cells." (PMID 35289120, 2022). "In summary, this study showed that chrysin inhibits tumor growth and VM by inhibiting HIF-1α, SPHK-1, and phospho-AKT/GSK-3β signaling in PC-3 cells under hypoxia." (PMID 36139362, 2022). "The q-PCR results validated these two ASEs, which were confirmed to play a key role in tumour metastasis and were located in the APOC1 (P = 0.0001) and SPHK1 genes (P = 0.0391)." (PMID 34857818, 2021). "Multivariate Cox regression analysis for PFS and OS included SPHK1 expression, age (> 50 vs. ≤ 50 years), FIGO stage (I and II vs. III and IV), histology (HGSOC vs. others) and residual tumor (0 vs. > 0 cm)." (PMID 33660008, 2021). "In the current study, we found that both phospho-SphK1 and phospho-SphK2 were significantly correlated with the FSHR level in tumour tissue." (PMID 32796926, 2020). "Depletion of SPHK1 by RNA interference has been reported to significantly reduce COX2 expression and PGE2 production, to inhibit tumor development, as well as to reduce cell proliferation and increase apoptosis in colon cell models." (PMID 31801289, 2019). "In our work, we consistent expression of SPHK1 with POTEE from both endogenous and exogenous evidence, and they are also positively correlated in the tumor samples of CRC patients." (PMID 31723122, 2019). "Numerous tumor promoting agonists including TNF-α and other inflammatory signaling molecules, such as IL-1β, IFN-γ, IgE, and C5a, stimulate cytosolic SphK1, which translocates to the plasma membrane and uses sphingosine as a substrate to generate S1P." (PMID 29987226, 2018). "Expression levels of these molecules are correlated with those of sphingosine kinase 1 (SPK1), VEGF and endothelial cell-specific molecule 1 (ESM1) in tumor tissues." (PMID 30477236, 2018).
tumor (continued). "This is consistent with in vitro studies indicating that SphK1 promotes HCC proliferation, migration, and epithelial–mesenchymal transition, crucial steps involved in HCC tumor progression and metastasis." (PMID 29510489, 2018). "The reduction in tumor load was confirmed by the measurements of mRNA levels of alpha-fetoprotein (AFP), a HCC biomarker, which was significantly reduced in SphK1−/− compared to WT mice." (PMID 29643998, 2018). "Elevated SphK1 has been shown in EOC cells and functionally involved in drug-resistance and other tumor promoting activities." (PMID 29987226, 2018). "Altogether, these data indicated that FTY720 is effective in inhibiting MM growth and this mechanism is, at least in part, mediated by re-activation of PP2A tumor suppression function via SET inhibitor displacement and suppression of SphK1 activity." (PMID 28298211, 2017). "SphK1 was also detected to be overexpressed in HNSCC cell lines, but down-expressed in JHU-22miR124 cells and tumor xenografts." (PMID 28212569, 2017). "However, the role of SPHK1 in cells of the tumor stroma remains unclear." (PMID 26716409, 2016). "In this study, we identified SPHK1, S1P, S1PR2, and p38 MAPK as essential for the TGF-β-mediated induction of myofibroblastic differentiation and the acquisition of a tumor-promoting CAF phenotype." (PMID 26716409, 2016). "We found that HULC up-regulated sphingosine kinase 1 (SPHK1), which is involved in tumor angiogenesis." (PMID 26540633, 2016). "Sphingosine kinase 1 (SPHK1), an oncogenic kinase, has previously been found to be upregulated in various types of human malignancy and to play a crucial role in tumor development and progression." (PMID 26311741, 2015). "The protein expression of SphK1 and EGFR in the tumor tissues from 180 patients was analyzed and compared to the expression in non-cancerous tissues." (PMID 25245676, 2014). "Our findings suggest that SPHK1 inhibition, which effectively counteracts oncogenic signaling through ERK1/2 and AKT pathways, is a potentially important anti-tumor strategy in TNBC." (PMID 25153718, 2014). "In a more recent effort to elucidate the role of SphK1 in HNSCC, Sinha and colleagues incorporated primary human HNSCC tumor tissues and murine HNSCC xenografts to show the apoptotic effect of silencing SphK1 on tumor growth." (PMID 24970177, 2013). "In line with our observations, SPHK1 expression relative to CXCR4 as well as CXCL12 relative to S1PR5 correlated positively in tumor biopsies but not in the respective normal control tissue." (PMID 40155684, 2025). "Early co-culture experiments of GBM tumor cells with endothelial cells demonstrated that blocking SPHK1 inhibited angiogenesis independent of VEGF signaling." (PMID 40507361, 2025). "Importantly, in vivo studies confirmed that combined therapy with the SPHK1 inhibitor PF-543, the TLR4 antagonist TAK-242, and TMZ synergistically suppressed tumor growth and significantly enhanced the efficacy of TMZ." (PMID 41353343, 2025). "Unlike SphK1, SphK2 remains understudied; nevertheless, it already appears to shape tumor fate by reprogramming transcriptional networks and cell-cycle checkpoints." (PMID 41234914, 2025). "The SPHK1-S1P signalling axis has also been reported promote the survival of breast CSCs through blocking the tumour suppressor function of signal transducer and activator of transcription 1 (STAT1), with SPHK1 inhibitors sensitising these cells to cell death induced by doxorubicin." (PMID 41253780, 2025). "Considering the paired sample differential analysis, expression correlation analysis, immunological and tumour microenvironment correlation analysis, as well as the line chart results, CEMACAM3, LCK, PARP1, PDGFB, PLK1, SEMA7A and SPHK1, were considered as prognostic genes of higher value." (PMID 39656479, 2024). "So, SPHK1 and TRAF6 as tumor promote factors are closely related in CRC, and SPHK1 may regulate the expression of TRAF6." (PMID 38135696, 2024).
tumor (continued). "On the day of tumor capture, IFN-γ and TNF-α ELISAs were performed on sera from HNSCC mouse models with knockout or overexpression of SPHK1/MMP1, with the results showing that SPHK1/MMP1 expression was negatively correlated with IFN-γ and TNF-α." (PMID 39629135, 2024). "Importantly, the combination of SPHK1/MMP1 knockdown and anti-PD-1 therapy produces more obvious tumor suppression and further alleviates CD8+ T-cell exhaustion." (PMID 39629135, 2024). "As discussed in detail in our recent publication, the enzyme sphingosine kinase 1 (SK1), which is overexpressed in many different tumors, may participate in tumor cell evasion of NKT cells responses." (PMID 37908366, 2023). "Due to the tumor-promoted mechanisms of HOXC11 remains unclear, we used GSEA to enrich some HOXC11 expression-related genes, including CCL5, HBA2, and SPHK1, and then detected their mRNA expressive levels in HOXC11 overexpressed cells." (PMID 36823149, 2023). "S1P, a bioactive sphingolipid metabolite being produced by one of two sphingosine kinase isoforms (SPHK1 or SPHK2), can be released through transporters into the tumor microenvironment to influence tumor cells as well as immune cells, contributing to carcinogenesis." (PMID 36600310, 2023). "We also showed that chrysin inhibits SPHK-1 and HIF-1α expression in tumor tissues." (PMID 36139362, 2022). "Altogether, both endogenous SPHK1-derived S1P and SPHK2-derived S1P have shown to function independent of their S1P receptor signaling by binding to specific intracellular targets, thereby regulating genes involved in tumor growth/progression." (PMID 35565311, 2022). "In addition, we performed IHC staining with both anti-SPHK1 and anti-PBX1 antibodies on NSCLC tumor specimens to measure the correlation between the two molecules." (PMID 36361531, 2022). "Since no information is available regarding immunohistochemical localization of SphK2, SGPP1, and LPP3 in OSCC, thus, in the present study, we have analyzed the expression of SphK1, SphK2, SGPP1, and LPP3 in tumor tissues from OSCC patients and benign oral mucosa by immunohistochemistry (IHC)." (PMID 35494957, 2022). "We further constructed gene modules in AT2 (LUAD) and basal (LUSC) cells, which revealed that many tumor-related genes in cells from stage-I patients, including PIGR, AZGP1, BTG2, EGR1, and LMO3 in AT2 cells from LUAD, and AQP3, SPHK1, PPT1, and PDIA6 were found in basal cells from LUSC." (PMID 35027529, 2022). "The presence of intracellular elevated SphK1 expression correlates with clinical failure and poor survival in HNSCC patients and S1P-targeted therapy was put forward as a possible inclusion for resistant, hard-to-treat, HNSCC tumours." (PMID 35158806, 2022). "Sphingosine kinase-1 (SphK1) enzymatic activity was assessed in human biopsies (10 nontumor and 12 tumor individual samples)." (PMID 35158767, 2022). "Targeting SPHK‐S1P‐S1PR signaling, including SP1, SPHK1, SPHK2, S1PR1, and S1PR2 by the use of specific inhibitors, represents an innovative strategy for anticancer therapy that has shown efficacy in in vitro studies and in tumor xenograft models." (PMID 34766135, 2021). "These discoveries raised the interesting possibility that SPHK1 and HAS2 might play important roles in tumor progression." (PMID 33506044, 2021). "In BC, sphingosine kinase 1, which is necessary for the generation of S1P and its receptor S1PR1 can induce the release of proinflammatory cytokines, macrophage infiltration, and tumor progression." (PMID 34777473, 2021). "This study demonstrated that PF-543 had potent in vitro and in vivo anti-tumor activity independent of SphK1 initial expression, which completely results from a regulated induction of necrosis and not of apoptosis." (PMID 32456134, 2020). "In conclusion, we demonstrated that SPHK1 is required for breast CSCs’ and non-CSCs’ survival through suppression of the tumor suppressor function of STAT1." (PMID 32260399, 2020).
tumor (continued). "We found that knockdown of either SphK1 or SphK2 effectively reduced IFITM1 and KAL1 expression indicating sphingolipid metabolism indeed regulates these cellular genes expression and functions to determine tumor cell survival." (PMID 32626514, 2020). "The SPHK1 sphingosine Kinase 1 isozyme has been largely studied and its several functions in tumor development have been demonstrated, while the SPHK2 has not been as well-studied." (PMID 32211323, 2020). "Interestingly, the differentiated HSkM+ cells displayed a significantly increased SPHK1 and SPHK2 protein content compared to the undifferentiated HSkM− control and the tumor cell lines." (PMID 31455837, 2020). "Accordingly, an elevated level of S1P in neoplasm tissue does not precisely follow the range of S1P/SPHK1 pathway stimulation in endometrial carcinoma." (PMID 31187044, 2019). "Furthermore, our results show that ABCC1 correlated with SPHK1 expression and suggests that S1P is exported by ABCC1 to the tumor microenvironment." (PMID 30018456, 2018). "The SPHK1 isozyme has been extensively characterized and its diverse functions in tumor progression documented, while SPHK2 has not been as well characterized and its primary physiological functions are controversial." (PMID 31891125, 2018). "In ER negative breast cancer high tumor levels of S1PR4 and SphK1 are associated with poor patient prognosis, and in HER2+ cells S1PR4/HER2+ signaling is associated with metastasis." (PMID 28415564, 2017). "The intensity of SPHK1 staining was variable between tumours, and was scored by 2 independent observers as negative, weak, moderate or strong." (PMID 26493335, 2015). "Accordingly, it is not possible to rule out the importance of S1P and SPHK1 on tumour cell viability in specific circumstances not tested in their experiments- which would include exposure to cytotoxics." (PMID 26493335, 2015). "This idea is further supported by recent work in the Ogretmen laboratory where it was demonstrated that systemic sphingosine kinase 1-generated S1P regulates metastatic potential, but not tumor S1P, via regulation of tumor S1PR2/Brms1 signaling." (PMID 24970174, 2013). "In this study, we report that the expression of Sphingosine Kinase 1 (SphK1) protein was preferentially elevated in MPM tumor tissues (49 epithelioid and 13 sarcomatoid) compared to normal tissue (n = 13)." (PMID 23028939, 2012). "High levels of SPHK1 expression were present in areas containing the primary SGC cells, whereas SPHK1 was undetectable or only marginally detectable in the adjacent noncancerous tissues in all tumor sections and in normal salivary gland tissues." (PMID 20846391, 2010). "Of note, in hormono-insensitive PC-3 cells, neither androgen deprivation in vitro nor castration in vivo had any effect on tumor growth and SphK1 activity." (PMID 19956567, 2009). "Interestingly, SPHK1 and CXCL12 expression also positively correlated in COAD tumor samples." (PMID 40155684, 2025). "It is worth noting that although both SphK1 and S1P lyase (SGPL1) mRNA are upregulated in HCC, the net level of S1P is decreased, which may be related to the imbalance of sphingolipid metabolism in the tumor microenvironment." (PMID 41234914, 2025). "However, it is unclear whether SPHK1 relies on TRAF6 to induce autophagy and thus promote tumor metastasis in CRC." (PMID 38135696, 2024). "Moreover, CH has shown to inhibit hypoxia-driven progression of vasculogenic mimicry during angiogenesis, which is a common characteristic feature observed in tumour microenvironments by reducing the expression of HIF-1α, SPHK-1 and phospho-Akt/GSK-3β signaling in cancer cells." (PMID 38966181, 2024). "Expression of SphK1 was higher in tumor cells compared to adjacent non-neoplastic cells." (PMID 35494957, 2022).